IGF2BP3 (insulin like growth factor 2 mRNA binding protein 3)
Diseases named in the same sentence as IGF2BP3 in open-access papers (continued):
Sharing a sentence is not in itself a finding about the gene and the disease.
bladder cancer (continued). "Together, our findings confirmed that IGF2BP3 served as a core m6A regulator in bladder cancer." (PMID 40083693, 2025). "CCK-8 assay results also showed that knocking down CDK6 gene expression could significantly reduce the IC50 of cisplatin in bladder cancer cells that were elevated due to over-expression of IGF2BP3." (PMID 40083693, 2025). "Additionally, immunohistochemical analysis indicated a correlation between increased IGF2BP3 expression and chemotherapy drug resistance in bladder cancer patients, suggesting its potential involvement in mediating resistance to chemotherapy." (PMID 40083693, 2025). "Similarly, EDU assay demonstrated that knockdown of CDK6 gene expression reversed the IGF2BP3 induced increase in DNA replication capacity of bladder cancer cells." (PMID 40083693, 2025). "Notably, IGF2BP3 exhibited high expression levels in bladder cancer patients, establishing it as an independent prognostic factor for bladder cancer." (PMID 40083693, 2025). "Moreover, targeting IGF2BP3 either through small molecule inhibitors or monoclonal antibodies represents a promising approach to resensitize bladder cancer cells to cisplatin, potentially improving treatment outcomes." (PMID 40083693, 2025). "Additionally, colony-forming assays provided further confirmation of the enhancing impact of IGF2BP3 on the growth of bladder cancer cells." (PMID 38504159, 2024). "And high IGF2BP3 levels were related to good prognosis in immunotherapy of bladder cancer." (PMID 38504159, 2024). "Moreover, IGF2BP3 expression positively correlated with inflammation and immune infiltration in bladder cancer." (PMID 38504159, 2024). "IGF2BP3-mediated SRD5A3 m6A modification induces acquired CDDP resistance in bladder cancer cells." (PMID 39680264, 2024). "This suggests that IGF2BP3 is likely to suppress autophagic cell death in bladder cancer cells." (PMID 38504159, 2024). "The specific functions and underlying mechanisms of IGF2BP3, as well as the potential benefits of targeting it for therapeutic purposes in bladder cancer, are not yet well comprehended." (PMID 38504159, 2024). "Of note, an upregulated IGF2BP3 may fuel disease progression, indicating an unfavorable prognostic factor in bladder cancer." (PMID 39680264, 2024). "Importantly, pharmacological inhibition of HMGB1 with glycyrrhizin, a specific HMGB1 inhibitor, effectively reversed the cancer-promoting effects of IGF2BP3 overexpression in bladder cancer." (PMID 38504159, 2024). "Collectively, our results indicate that IGF2BP3 promotes HMGB1 stability by directly binding to HMGB1 mRNA through m6A modification in bladder cancer cells and suggest a potential role for IGF2BP3 in modulating the immune response in BLCA and its impact on immunotherapy efficacy." (PMID 38504159, 2024). "Our results revealed an upregulation of IGF2BP3 in bladder cancer tissues and IGF2BP3 knockdown could reduce bladder cancer cell proliferation, prevent CDDP resistance, induce cell apoptosis, and inhibit bladder tumorigenesis in mice." (PMID 39680264, 2024). "This indicated a potential role of IGF2BP3 in bladder cancer proliferation." (PMID 38504159, 2024). "Bladder cancer cell lines showed a relatively high level of IGF2BP3 compared with SV-HUC-1 cells." (PMID 36732736, 2023). "Along with the decreasedIGF2BP3 mRNA levels, there was also a significant down-regulation of PD-L1 mRNA expression, indicating that IGF2BP3 may participate in the immune response of bladder cancer through PD-L1." (PMID 36732736, 2023). "IGF2BP3 is highly expressed in bladder cancer and may sustain cell growth by activating the JAK/STAT pathway." (PMID 37663284, 2023). "Although four types of RBPs have been listed for their roles and functions in bladder cancer, more RBPs have been identified and reported in bladder cancer, including insulin-like growth factor messenger RNA binding protein 3 (IGF2BP3), nucleolin (NCL), and quaking (QKI)." (PMID 36831493, 2023).
bladder cancer (continued). "Compared with IGF2BP3, which has been widely reported in a variety of tumors such as breast, liver, and gastrointestinal tract tumors, pancreatic cancer, and lung cancer, knowledge on its role in bladder cancer is limited." (PMID 36831493, 2023). "In addition, researchers have revealed the regulatory relationship between IGF2BP3 and PD-L1 in bladder cancer." (PMID 37298373, 2023). "Finally, we detected IGF2BP3 expression in our bladder cancer samples and clarified the effect of IGF2BP3 on bladder cancer cell migration and invasion." (PMID 36732736, 2023). "Positive IGF2BP3 staining was mainly detected in the cytoplasmic in the bladder cancer tissues." (PMID 36732736, 2023). "In addition, our results showed a positive correlation between the expression level of IGF2BP3 and the bladder cancer stage." (PMID 36732736, 2023). "IGF2BP3 also participates in the construction of prediction models for bladder cancer." (PMID 37298373, 2023). "Our study suggests that IGF2BP3 could be used as a prognosis marker in bladder cancer and promotes the progression through PD-L1." (PMID 36732736, 2023). "Furthermore, PM2.5-induced m6A modification regulates the mRNA stability of BIRC5 through METTL3/IGF2BP3, thus promoting the proliferation and metastasis of bladder cancer." (PMID 37298373, 2023). "IGF2BP3 also exerts a significant impact on PD-L1 expression in bladder cancer." (PMID 37280679, 2023). "However, in bladder cancer, as the only reported IGF2BP3, its molecular mechanism in regulating bladder cancer is still not elucidated." (PMID 36831493, 2023). "Furthermore, they confirmed that IGF2BP3 positively regulates the expression of PD-L1 in bladder cancer." (PMID 37298373, 2023). "On conclusion, IGF2BP3 might be a potential therapeutic target of bladder cancer that can greatly change the prognosis of patients." (PMID 37598390, 2023). "Furthermore, increased expression of IGF2BP3 significantly correlated with reduced overall survival for patients with bladder cancer." (PMID 36732736, 2023). "Furthermore, the correlation between IGF2BP3 and PD-L1 in patients with BCa showed a trend similar to that of bladder cancer cell lines from CCLE." (PMID 35148766, 2022). "In the present study, results of clinically relevant study suggested that bladder cancer patients with higher IGF2BP3 levels were more prone to poor overall survival, and higher IGF2BP3 expression was correlated with a significantly increased risk of death in bladder cancer patients." (PMID 33094561, 2020). "The results showed that IGF2BP3 was overexpressed in bladder cancer tissues compared with that in normal bladder tissues, and its higher expression was closely correlated with poor prognosis in bladder cancer patients." (PMID 33094561, 2020). "Furthermore, we assessed the expression of IGF2BP3 with Western blotting in 5 pairs of bladder cancer and matched normal adjacent tissues." (PMID 33094561, 2020). "Hence, IGF2BP3 facilitated bladder cancer cell proliferation by activating the JAK/STAT signalling pathway." (PMID 33094561, 2020). "Next, a transwell assay was performed to determine whether IGF2BP3 affected the migratory and invasive potential of bladder cancer cells." (PMID 33094561, 2020). "As decreasing the IGF2BP3 expression greatly inhibited cell viability, it was hypothesized that IGF2BP3 may affect cell apoptosis in bladder cancer cells." (PMID 33094561, 2020). "Hence, these findings suggest that IGF2BP3 is highly expressed in bladder cancer and that IGF2BP3 is a factor for predicting poor survival in patients with bladder cancer." (PMID 33094561, 2020). "Therefore, we conclude that IGF2BP3 functions as a tumour promotor via JAK/STAT signalling pathway in bladder cancer development." (PMID 33094561, 2020).
bladder cancer (continued). "Firstly, the number of bladder cancer cells passed through the transwell membrane was observed to be reduced by siRNA‐mediated knockdown of IGF2BP3 in T24, suggesting that silencing IGF2BP3 could inhibit cell migration in bladder cancer." (PMID 33094561, 2020). "Our study showed that IGF2BP3 could be a prognostic factor in bladder cancer and serve as a potential target for new therapeutic strategies." (PMID 33094561, 2020). "Additionally, we further discovered IGF2BP3 promote cell growth of bladder cancer cells via JAK/STAT signalling." (PMID 33094561, 2020). "In our study, we found IGF2BP3 could promote tumorigenesis of bladder cancer by JAK/STAT signalling." (PMID 33094561, 2020). "Consistent with previous studies, our study demonstrated that IGF2BP3 could be considered to play an oncogenic role in the progression of bladder cancer by promoting cell growth." (PMID 33094561, 2020). "We investigated the relation between IGF2BP3 expression and prognosis of bladder cancer patients." (PMID 33094561, 2020). "However, the specific mechanism and potential function of IGF2BP3 in cisplatin resistance of bladder cancer remain unclear." (PMID 40083693, 2025). "Finally, the IGF2BP3 knockdown T24 cells or control group were injected under the skin of nude mice to establish an animal model to observe whether the expression of IGF2BP3 in animals affected the sensitivity of bladder cancer to cisplatin." (PMID 40083693, 2025). "Similarly, IGF2BP3 recognizes and stabilizes m6A-modified circPSMA7 in bladder cancer." (PMID 41318550, 2025). "Correlation analysis in bladder cancer samples from TCGA BLCA demonstrated a positive correlation between mRNA levels of IGF2BP3 and SNAI1 (Snail), SNAI2 (Slug), CDH2 (N-cadherin), VIM (vimentin), and MMP9, further supporting the association between IGF2BP3 and EMT-related markers." (PMID 38504159, 2024). "Notably, SRD5A3 and IGF2BP3 were highly expressed in bladder cancer tissues and cell lines." (PMID 39680264, 2024). "Therefore, we investigated whether IGF2BP3 expression was correlated with immune infiltration levels in bladder cancer." (PMID 36732736, 2023). "However, currently, only IGF2BP3 has been reported in bladder cancer." (PMID 36831493, 2023). "However, little is known about the function of IGF2BP3 in bladder cancer." (PMID 33094561, 2020). "However, the biological functions of IGF2BP3 in bladder cancer are poorly understood." (PMID 33094561, 2020). "However, the role of IGF2BP3 in driving proliferation of bladder cancer has yet be elucidated." (PMID 33094561, 2020). "To evaluate cell proliferation when CDK6 interacted with IGF2BP3 in bladder cancer, we transfected CDK6 small interfering RNA (siCDK6) or control (SCR) into over-expressed IGF2BP3 cells." (PMID 40083693, 2025). "Meanwhile, IGF2BP3 enhanced the stability of oncogene HMGB1 by binding to its mRNA and promoted the expression of HMGB1 in bladder cancer." (PMID 40083693, 2025). "The expressions of IGF2BP1, IGF2BP3, YTHDF1, YTHDF2, and HNRNPC were significantly up-regulated in bladder cancer." (PMID 40083693, 2025). "The IHC analysis of TMA from bladder cancer revealed a significant positive correlation between the expression of CDK6 and IGF2BP3." (PMID 40083693, 2025). "IGF2BP3-mediated mRNA stability of multiple oncogenes, such as CDK2 and STAT3 via a m6A-dependent manner, have been found to promote the development of bladder cancer." (PMID 39680264, 2024). "It was also showed that IGF2BP3 was lowly expressed at the mRNA and protein levels in standard SV-HUC-1 cells compared to bladder cancer cells (T24 and 5637)." (PMID 39680264, 2024). "The present research revealed that expression of IGF2BP3, acting as a positive regulator of HMGB1, exhibited a positive correlation with the degree of immune cell infiltration in bladder cancer." (PMID 38504159, 2024).
bladder cancer (continued). "In conclusion, our results demonstrate that IGF2BP3 is negatively regulated by promoter methylation and miR-320a-3p, but positively regulated by CNA in bladder cancer." (PMID 38504159, 2024). "GSEA analysis indicated a positive correlation between IGF2BP3 levels and “INFLAMMATORY RESPONSE” and “ALLOGRAFT REJECTION” in bladder cancer datasets." (PMID 38504159, 2024). "It was found in humans and animal models that METTL3, FTO, IGF2BP1, IGF2BP3, YTHDF1, YTHDF 2, ELAV-like protein 1 (ELAVL1), HNRNPA2B1 were upregulated in bladder cancer cells." (PMID 37701836, 2023). "The expression of IGF2BP3 in normal human bladder epithelial cells (SV-HUC-1) and bladder cancer cell lines (5637, J82, UMUC3 and T24) was validated by qRT-PCR." (PMID 36732736, 2023). "Among them, a significant difference in expression between bladder cancer and normal tissue in the TCGA-BLCA cohort is only detected in IGF2BP3." (PMID 36189296, 2022). "Chi-square test analysis showed that the expression of IGF2BP3 in patients with bladder cancer was correlated with gender (P=0.025), but not with age, stage, grade, and tumor size." (PMID 40083693, 2025). "To validate this hypothesis, we quantified mRNA levels of both IGF2BP3 and CDK6 in 44 pairs of bladder cancer tissues and adjacent normal tissues." (PMID 40083693, 2025). "Results of qRT-PCR and immunoblotting analysis displayed elevated mRNA and protein levels of IGF2BP3 in the tumor tissues of 30 bladder cancer patients than the matched adjacent non-tumor bladder tissues." (PMID 39680264, 2024). "Our findings indicate that the expression of IGF2BP3 increases due to promoter hypomethylation, copy number gain/amplification, and a lack of miR320a-3p in bladder cancer." (PMID 38504159, 2024). "Consistently, we observed a notable elevation in IGF2BP3 transcript levels in bladder cancer tissues compared to normal tissues." (PMID 38504159, 2024). "Therefore, the combined treatment with CDDP and specific inhibitors for IGF2BP3 or m6A, can be considered in a clinical setting to overcome intrinsic or acquired resistance to CDDP in bladder cancer patients." (PMID 39680264, 2024). "This suggests that IGF2BP3 may not only promote EMT by inhibiting KLF4, but also prevent bladder cancer cell differentiation." (PMID 38504159, 2024). "Nevertheless, the precise functional significance of IGF2BP3 in the advancement of bladder cancer is still not well understood." (PMID 38504159, 2024). "Therefore, we concluded that SRD5A3 and IGF2BP3 play oncogenic roles in bladder tumorigenesis, and IGF2BP3 directly interacts with SRD5A3 mRNA and increases its stability during cisplatin resistance development in bladder cancer." (PMID 39680264, 2024). "FTO, IGF2BP3, and YTHDC1 have a significant difference in bladder cancer and prognosis." (PMID 35251177, 2022). "Furthermore, through immunohistochemical studies of tissue microarrays, we assessed the expression of IGF2BP3 and phosphorylation of STAT3 in bladder cancer tissues." (PMID 33094561, 2020). "Compared with adjacent noncancerous tissues, we found that the protein levels of IGF2BP3 were higher in bladder cancer tissues." (PMID 33094561, 2020). "However, the involvement of IGF2BP3 in m6A manner has not been reported in bladder cancer." (PMID 40083693, 2025). "In conclusion, our study demonstrated that IGF2BP3 regulated the cell cycle and cisplatin sensitivity in bladder cancer by enhancing CDK6 mRNA stability in an m6A-dependent manner, which maybe providing a new treatment strategy for bladder cancer patients, especially those with cisplatin resistance." (PMID 40083693, 2025). "However, the role of IGF2BP3 in bladder cancer has not been well clarified." (PMID 36732736, 2023).
leukemia (28 papers, 2013 to 2025). A malignant (clonal) hematologic disorder, involving hematopoietic stem cells and characterized by the presence of primitive or atypical myeloid or lymphoid cells in the bone marrow and the blood. "IGF2BP3 targets mRNAs encoding important factors in leukemia, like MYC, CDK6, HOXA genes, and EPOR, causing their stabilization and overexpression in leukemia cells." (PMID 40389480, 2025). "IGF2BP1 and IGF2BP3 have been linked to leukemia, as well as solid malignancies, and are often co-expressed with LIN28B." (PMID 38601080, 2024). "Utilizing an Ig2bp3 knockout MLL-Af4 driven leukemia mouse model, we determined that Igf2bp3 deficiency significantly increased the survival of MLL-Af4 transplanted mice and decreased the numbers and self-renewal capacity of MLL-Af4 LICs." (PMID 36307883, 2022). "Following transplantation of transduced HSPCs, Igf2bp3 loss significantly increased both leukemia-free and overall survival of MLL-Af4 mice." (PMID 34321607, 2022). "Here, we found that deletion of Igf2bp3 in MLL-Af4 leukemia caused a striking delay in leukemia development and significantly increased the survival of MLL-Af4 mice." (PMID 34321607, 2022). "In our efforts to understand the effects of IGF2BP3 on leukemia cell metabolism, we uncovered an impact on glycolysis and OCM." (PMID 41015030, 2025). "In MLL-AF4 leukemia, the deletion of IGF2BP3 mediated by CRISPR/Cas9 sensitizes MLL-AF4 leukemia to the effects of menin-MLL inhibition on cell growth and leukemic initiating cells in vitro, which shows potent antileukemic effects." (PMID 40958857, 2025). "As early as 2005, the insulin-like growth factor 2 mRNA binding protein 3 (IGF2BP3) was identified to promote the proliferation of human K562 leukemia cells by targeting IGF2 leader-3 mRNA." (PMID 39342091, 2024). "Depletion of the murine paralog IGF2BP3 increases the latency of leukemia in murine models of KMT2A::AFF1 AML." (PMID 38601080, 2024). "Although the function of IGF2BP3 in other types of hematological malignancies is unclear, a promoting role of IGF2BP3 in leukemia has been identified." (PMID 37298373, 2023). "The deletion of Igf2bp3 significantly increased mouse survival and reduced the number and self-renewal capacity of leukemia-initiating cells." (PMID 37298373, 2023). "In acute myeloid leukemia, IGF2BP3 is indispensable for leukemia cell survival by enhancing RCC2 expression through the interaction between IGF2BP3 and m6A sites in RCC2 mRNA." (PMID 37280679, 2023). "Together, our findings show that IGF2BP3 represents an attractive therapeutic target in this disease, providing important insights into mechanisms of posttranscriptional regulation in leukemia." (PMID 34321607, 2022). "IGF2BP3 was overexpressed in patients’ bone marrows, the levels of the protein correlating with extent of proliferation of leukemia cells and poor prognosis." (PMID 35217832, 2022). "Jianchuan Deng and co-workers at Chongqing Medical Universit0y, China, examined the role of an m6A-related protein called IGF2BP3 in mice models and samples from leukemia patients." (PMID 35217832, 2022). "Deletion of Igf2bp3 significantly increases the survival of mice with MLL-Af4-driven leukemia and greatly attenuates disease, with a minimal impact on baseline hematopoiesis." (PMID 34321607, 2022). "At the cellular level, MLL-Af4 leukemia-initiating cells require Igf2bp3 for their function in leukemogenesis." (PMID 34321607, 2022). "The m6A binding proteins, such as IGF2BP3, should be further explored as biomarkers for leukemia type, as prognostic factors and, ultimately, as therapeutic targets in hematological malignancies." (PMID 35217832, 2022). "It has been further determined that IGF2BP3 is required for efficient initiation of MLL-Af4 leukemia and LIC function." (PMID 36226062, 2022). "Our findings highlight IGF2BP3 as a necessary regulator of MLL-AF4 leukemia and a potential therapeutic target for this disease." (PMID 34321607, 2022).